NRF1 (nuclear respiratory factor 1)
Diseases named in the same sentence as NRF1 in open-access papers (continued):
Sharing a sentence is not in itself a finding about the gene and the disease.
Adrenal insufficiency (1 paper, 2019). Insufficient production of steroid hormones (primarily cortisol) by the adrenal glands. "We postulate that patients with NGLY1 deficiency may develop adrenal insufficiency as a consequence of impaired proteostasis, and the accompanying proteotoxic stress‐induced cell death, through defective Nrf1 function." (PMID 30740912, 2019).
alcoholic hepatitis (1 paper, 2025). Acute hepatitis resulting from ingestion of alcohol. "Mechanistic studies in the livers of patients with alcoholic hepatitis revealed that upregulated ATF4 represses the transcription activity of nuclear respiratory factor 1 (Nrf1), a major transcriptional regulator of mitochondrial biogenesis, attenuating mitochondrial damage." (PMID 39940664, 2025).
asthma (1 paper, 2011). "In severe asthma, an abnormal extracellular calcium entry leads to subsequent activation of peroxisome proliferator-activated receptor γ coactivator-1α (PGC-1α), nuclear respiratory factor-1 (NRF-1), and mitochondrial transcription factor A (mtTFA)." (PMID 22220184, 2011).
autosomal dominant optic atrophy (1 paper, 2018). An autosomal dominant hereditary condition characterized by optic atrophy and progressive visual loss. "It is noteworthy that mutations in human OPA1, a direct target of human NRF1, are the cause of autosomal dominant optic atrophy, which leads to retinal ganglion cell death." (PMID 30333037, 2018).
Brain atrophy (1 paper, 2020). Partial or complete wasting (loss) of brain tissue that was once present. "Interestingly, brain-specific knockout of NRF1 in mice results in the age-dependent increase in aggregated proteins, brain atrophy, and decreased motor capacity, as is observed in neurodegenerative disease." (PMID 33096892, 2020).
carcinoid (1 paper, 2021). "The NRF1 mutations, mainly associated with the NSCLC, were reported by La Rosa as shared by both component adenocarcinoma/carcinoid, but their role in the pathogenesis of mixed component remains unknown." (PMID 34926584, 2021).
cholestasis (1 paper, 2020). Impairment of the bile flow caused by obstruction within the liver, or outside the liver in the bile duct system. "Sirt6 activated the PGC-1α/NRF1, NRF2 pathway by activating AMPK phosphorylation and directly deacetylating PGC-1α, which revealed Sirt6 as a promising therapeutic target in cholestasis-induced biliary epithelial cell injury." (PMID 32206298, 2020).
colitis (1 paper, 2025). Inflammation of the colon. "CKMT1 knockout did not significantly impact the expressions of Nrf1, Ppara, Tfam, Tomm20, or Nfe2l2 during colitis." (PMID 40089459, 2025).
disc degeneration (1 paper, 2023). "It was also found that NRF1 induces autophagy and inhibits apoptotic responses by promoting Atg7 expression in compressed NP cells, delaying disc degeneration." (PMID 37915003, 2023).
dopaminergic neuroblastoma (1 paper, 2014). A neuroblastoma associated with increased dopamine excretion. "Our results indicated the same decrease in mRNA level of PGC1α, NRF1 and ATPase5β in human dopaminergic neuroblastoma-derived cells in tissue culture (SHSY5Y), stably expressing mutant GCase in comparison to their level in the same cells expressing normal GCase." (PMID 24935484, 2014).
endometriosis (1 paper, 2020). The growth of functional endometrial tissue in anatomic sites outside the uterine body. "It has been reported that ERβ plays an important role in EMS pathogenesis by modulating its target genes, including NRF1, SOD2, COX2, and MMP1, and specific ERβ suppression, such as ERβ antagonist, has been used for treatment of endometriosis, but with many of limitations and side effects." (PMID 33362719, 2020).
experimental autoimmune encephalomyelitis (1 paper, 2025). An autoimmune demyelinating disease of the central nervous system that is produced experimentally in animals by the injection of homogenized brain or spinal cord in Freund's adjuvant. "Similarly imbalanced immune activation and inflammation were unveiled in experimental autoimmune encephalomyelitis, which may be caused by a combination of proteasomal subunit displacement and reduced Nrf1 expression." (PMID 40703332, 2025).
fetal growth restriction (1 paper, 2020). A fetus that does not grow beyond the 10th percentile of conventionally accepted weight for gestational age. "Therefore, we suggest that elevated T plays an important role in causing mitochondrial dysfunction in the placenta, and the suppressed PGC-1α and NRF-1 expression and function might contribute to the reduced mitochondrial function and the associated placental and fetal growth restriction." (PMID 32698476, 2020).
fibrosarcoma (1 paper, 2022). A malignant mesenchymal fibroblastic neoplasm affecting the soft tissue and bone. "Nuclear Nrf2 heterodimerizes with musculoaponeurotic fibrosarcoma (Maf) to recognize ARE and promote the transcription of antioxidant genes, including Nrf1, HO–1, and NQO1." (PMID 36678511, 2022).
folate deficiency (1 paper, 2023). A nutritional condition produced by a deficiency of FOLIC ACID in the diet. "The role of folate deficiency in inducing changes in mitochondrial function was examined by measuring changes in gene expression of the PGC-1α/NRF-1 signaling cascade, as well as changes in relative mtDNA content." (PMID 37981683, 2023).
gastric adenocarcinoma (1 paper, 2017). "Next, we investigated the effects of 17-DMAG on the expression of NRF-1 and antioxidant enzymes in ex vivo cultures of gastric tissues obtained from patients who underwent gastrectomies (paired normal stomach and gastric adenocarcinoma tissues from each patient, N = 10)." (PMID 28915605, 2017).
glaucoma (1 paper, 2018). Increased pressure in the eyeball due to obstruction of the outflow of aqueous humor. "Thus, it would be interesting to test whether downregulation of Nrf1 contributes to RGC death in several glaucoma animal models." (PMID 30333037, 2018).
Glucose intolerance (1 paper, 2025). Glucose intolerance (GI) can be defined as dysglycemia that comprises both prediabetes and diabetes. "Thereby, the pathological phenotype of pancreatic Nrf1-KO mice is likely to account for ensuing glucose intolerance." (PMID 40703332, 2025). "Coincidently, β-cell-specific Nrf1-KO mice exhibit severe fasting hyperinsulinemia, as accompanied by reduced GSIS and glucose intolerance." (PMID 40703332, 2025).
HCMV infection (1 paper, 2022). "In addition, the genes relate to mitochondrial biogenesis (PGC-1α, TFAM, and NRF1) and oxidative phosphorylation (ATP5G1 and Cox5a) were also decreased after HCMV infection." (PMID 35359726, 2022).
heart injury (1 paper, 2015). Injury to the heart. "We also observed the expression of the key mitochondrial biogenesis signaling pathway PGC-1α–NRF1/NRF2 to characterize the cellular and molecular mechanism of exhaustive exercise-induced heart injury." (PMID 26167242, 2015).
hyperthyroidism (1 paper, 2025). Overactivity of the thyroid gland resulting in overproduction of thyroid hormone and increased metabolic rate. "However, despite activation of the upstream regulator NRF1, the level of TFAM protein, which is the final effector directly responsible for mitochondrial DNA replication and transcription, reduced in hyperthyroidism." (PMID 41369368, 2025).
invasive ductal breast carcinoma (1 paper, 2018). The most common type of invasive breast carcinoma, accounting for approximately 70% of breast carcinomas. "A significantly higher proportion of invasive ductal breast carcinomas overexpressed NRF1 in the nuclei compared to normal breast tissues (27 out of 40 tumors)." (PMID 30486409, 2018).
iron deficiency (1 paper, 2022). "Transcription factor enrichment and correlation analysis identified key transcription factors that were activated in both cultured cells and tissue by iron deficiency, including those implicated in iron regulation, such as HIF1, NFY, and NRF1." (PMID 35056799, 2022).
lactic acidosis (1 paper, 2019). Metabolic acidosis characterized by the accumulation of lactate in the body. "Although some tumor cell lines (A-549 and MCF-7) maintained increased levels of NRF-1, NRF-2 and TFAM, lactic acidosis promoted the increase in NRF-1, NRF-2, and TFAM transcript levels, only when the tumor cells expressed low levels of the transcription factors." (PMID 31681589, 2019).
latent infection (1 paper, 2024). "LMP2A-regulated Nrf1 expression maintains latent infection by Epstein–Barr virus through the NF-κB pathway." (PMID 39198723, 2024).
lentivirus infection (1 paper, 2022). Virus diseases caused by the Lentivirus genus. "To verify the function of NRF1 in microglial activation, we modulated NRF1 levels by lentivirus infection." (PMID 35704676, 2022).
liver cirrhosis (1 paper, 2026). "Interestingly, serum alanine aminotransferase (ALT) values were negatively correlated with Nrf1 expression in liver biopsies from MASH or liver cirrhosis patients, respectively." (PMID 41424862, 2026).
liver inflammation (1 paper, 2026). "By elucidating the molecular pathways through which the Nrf1-Foxo1 axis regulates liver inflammation, our finding provides a basis for developing innovative therapeutic strategies targeting macrophage-driven liver inflammation and fibrosis." (PMID 41424862, 2026).
lymphoma (1 paper, 2022). A malignant (clonal) proliferation of B- lymphocytes or T- lymphocytes which involves the lymph nodes, bone marrow and/or extranodal sites. "NRF1, a transcription factor, has been shown to be an important component of the DNA repair network in response to UVB-induced DNA damage, and NRF1 can also regulate circRNAs to promote lymphoma progression." (PMID 36281462, 2022).
male infertility (1 paper, 2024). The inability of the male to effect fertilization of an ovum after a specified period of unprotected intercourse. "The conditional ablation of NRF1 in gonocytes dramatically down-regulates several germline genes (Dazl, Lin28a, Ddx4), blocks germ cell proliferation, and subsequently leads to male infertility in mice suggesting an important role of NRF1 in regulation of some GRRs." (PMID 38715099, 2024).
mantle cell lymphoma (1 paper, 2020). Mantle cell lymphoma is a rare form of malignant non-Hodgkin lymphoma affecting B lymphocytes in the lymph nodes in a region called the ``mantle zone''. "TCF11/Nrf1-mediated proteasome re-synthesis is an attractive target for therapeutic intervention, especially for MM and mantle cell lymphoma, which are currently treated with proteasome inhibitors." (PMID 32344880, 2020).
MELAS (1 paper, 2020). "While one study showed comparable expression of Nrf1 and Tfam and upregulation of PGC-1α and SIRT3 in MELAS patients compared to controls, another one reported similar expression rates of PGC-1α and upregulation of Tfam in patients compared with that of controls." (PMID 32722320, 2020).
myocarditis (1 paper, 2024). Myocarditis is a condition that is characterized by inflammation of the heart muscle (myocardium). "We show that females with myocarditis have higher expression of several master regulators of mitochondrial homeostasis including PGC1α, NRF1 and ERRα compared to males." (PMID 39696682, 2024). "We found that NRF1 RNA levels were significantly decreased when males and females with myocarditis were combined compared to controls (p < 0.0001)." (PMID 39696682, 2024). "This was also observed when NRF1 levels were examined in males with myocarditis versus controls (p < 0.0001) or females with myocarditis versus controls (p < 0.0001)." (PMID 39696682, 2024). "However, NRF1 levels in the heart during myocarditis were significantly higher in females compared to males (p = 0.0315)." (PMID 39696682, 2024). "Similar to PGC1α and NRF1, we found that females had significantly higher levels of ESRRA transcript during myocarditis compared to males (p = 0.0128)." (PMID 39696682, 2024).
nasal polyp (1 paper, 2020). "Our finding showed that the expression of mitochondrial biogenesis markers such as NRF1, NRF2, TFAM, and COX4 was decreased in the epithelium of nasal polyp." (PMID 33598458, 2020). "Moreover, the decreased expression of NRF1, NRF2, TFAM, and COX4 was also observed in the nasal epithelium and nasal polyps by immunohistochemical staining." (PMID 33598458, 2020).
nosocomial infection (1 paper, 2024). An infection acquired in a hospital or other healthcare setting. "Based on the results from MDS analyses, we focused the analyses evaluating the association between nosocomial infection occurrence and NK cell-specific CPT1a and NRF1 expression." (PMID 38426112, 2024). "Collectively, our results revealed that NK cells were the predominant immune cell type, and CPT1a and NRF1 were the principal metabolic regulators associated with the risk of nosocomial infection." (PMID 38426112, 2024). "This analysis indicated that CPT1a and NRF1 expression levels in NK cell subsets and plasma IL-15 levels are strongly associated with nosocomial infection risk." (PMID 38426112, 2024). "In conclusion, our findings shed light on the role of perturbed NK cell immunometabolism, including NRF1 downregulation and CPT1a upregulation, in the risk of nosocomial infection in CCI." (PMID 38426112, 2024). "Notably, downregulation of intracellular NRF1 in the NK cell population and subpopulations was significantly associated with an increased risk of nosocomial infection, whereas CPT1a was upregulated in all NK cell subpopulations from patients who developed nosocomial infection." (PMID 38426112, 2024). "Downregulated NRF1 and upregulated CPT1a were found in all subsets of NK cells from patients who developed a nosocomial infection." (PMID 38426112, 2024). "Here, through unbiased exploration, we uncovered the association between NK cell-specific immunometabolism, in particular the altered expression of NRF1 and CPT1a, and nosocomial infection in patients with CCI." (PMID 38426112, 2024). "Although the transcriptional regulation activity of NRF1 is regulated by PGC1α, the levels of PGC1α in NK cells are not correlated with the risk of nosocomial infection." (PMID 38426112, 2024). "Compared to subjects without nosocomial infection, those with nosocomial infection exhibited an increased abundance of a specific cluster which is characterized by elevated CPT1a expression and reduced NRF1 expression." (PMID 38426112, 2024).
oral squamous cell carcinoma (1 paper, 2025). "Ferroptosis of oral squamous cell carcinoma was also restrained by Nrf1-target holiday junction recognition protein (HJURP), leading to the cancer progression." (PMID 40703332, 2025).
osteoarthritis (1 paper, 2020). A noninflammatory degenerative joint disease occurring chiefly in older persons, characterized by degeneration of the articular cartilage, hypertrophy of bone at the margins and changes in the synovial membrane. "Specifically, in a study to develop a therapeutic strategy for osteoarthritis, Que was shown to increase expression levels of SIRT1, PGC-1α, NRF1 and NFR2, TFAM, and phospho-AMPK α in osteoarthritis rats, confirming the hypothesis that Que might act via the AMPK/SIRT1 signaling pathway." (PMID 32848804, 2020).
osteoporosis (1 paper, 2025). A condition of reduced bone mass, with decreased cortical thickness and a decrease in the number and size of the trabeculae of cancellous bone (but normal chemical composition), resulting in increased fracture incidence. "This indicates differential and even opposing roles of multiple distinct Nrf1 isoforms in the osteoclast genesis and differentiation, bone remodeling and metabolism homeostasis, to provide an understanding of the pathogenesis of various bone disorders including osteoporosis and arthritis." (PMID 40703332, 2025).
Peritoneal Fibrosis (1 paper, 2022). Disorder characterized by a wide range of structural changes in PERITONEUM, resulting from fibrogenic or inflammatory processes. "In this study, we observed the downregulation of PGC-1α signaling, which was manifested by decreased protein expression of PGC-1α, NRF-1, NRF-2 and TFAM and PGC-1α mRNA expression in high glucose-based PD fluid-induced peritoneal fibrosis." (PMID 36148521, 2022).
pleural plaques (1 paper, 2023). "In subjects with pleural plaques, carriers of at least one polymorphic NRF1 rs13241028 C allele had lower calretinin than carriers of two wild-type alleles in the dominant model (P = 0.025)." (PMID 38038422, 2023).
prediabetes (1 paper, 2017). "Nrf-1 expression has also shown to be inversely related to fasting blood glucose levels and expression of NRF-1 dependent genes has been observed in prediabetes subjects in conjunction with lower Pgc-1α." (PMID 28420087, 2017).